IL1B (interleukin 1 beta)
Diseases named in the same sentence as IL1B in open-access papers (continued):
Sharing a sentence is not in itself a finding about the gene and the disease.
prostate carcinoma (continued). "IL-1β has an antiproliferative effect on prostate cancer cells, enhanced by coculture with normal fibroblasts, through IL-6." (PMID 32635472, 2020). "Together, our findings provide evidence that CTH generated H2S promotes prostate cancer progression and metastasis through IL‐1β/NF‐κB signaling pathways." (PMID 31468690, 2019). "AIM2, an interferon (IFN) inducible protein, is constitutively down-regulated in prostate cancer, however, IFN-induced AIM2 inflammasome activation leads to increased production of IL-1β and IL-18 in prostate cancer cell lines." (PMID 30631327, 2018). "IL-1β expression is high in AR-negative prostate cancer cells, but IL-1β also represses AR expression and promotes bone metastasis." (PMID 30158439, 2018). "In line with this and in contrast to IL-1β, overexpression of IL-18 in prostate cancer cells inhibits tumor growth in vivo." (PMID 30158439, 2018). "The inflammasome complex proteins ASC (apoptosis-associated speck-like protein containing a CARD) and pro-caspase-1, as well as its downstream targets IL-1β and IL-18 were confined to aggressive prostate cancer cells." (PMID 28663562, 2017). "The downstream targets, IL-1β and IL-18 pro-forms were primarily confined to aggressive prostate cancer cell lines PC3 and DU145." (PMID 28663562, 2017). "Elevated expression level of AIM2 in senescent prostate epithelial cells is associated with increased IL-1β production and development of benign prostatic hyperplasia, whereas the expression of AIM2 in prostate cancer cells is low." (PMID 28526809, 2017). "While IL-18 pro-form is low to non-detectable in LNCaP, LN3, 22Rv1, and VCaP, a longer incubation also revealed a very low expression of IL-1β pro-form in prostate cancer cell lines." (PMID 28663562, 2017). "In support of this concept, one previous study mentioned that BM adipocytes modulate the fatty acid binding protein 4 (FABP4)-interleukin-1 beta (IL-1β) pathway in prostate cancer cells, when homing into bone." (PMID 27049717, 2016). "IFNs treated prostate cancer cell lines showed increased AIM2 activating inflammasome complex leading to production of IL-1β and IL-18." (PMID 27429614, 2016). "The most compelling evidence for a role of IL-1B in bone metastasis was reported using a mouse model of prostate cancer." (PMID 27765923, 2016). "A peptide mimicking this region reverts IL-1β induced NCoR dismissal when microinjected in prostate cancer cell nuclei." (PMID 27992601, 2016). "The effects of the cytokines TNF-α, TRAIL, IFN-γ, IFN-α, IFN-β, IL-13, and IL-1β on cell death and/or cell viability have been investigated in various prostate carcinoma cell lines such as LNCaP, PC-3, DU-145, and M12." (PMID 24982891, 2014). "Collectively, in prostate cancer patients an immediate elevation of IL-1β and IL-6 in plasma following irradiation has also been demonstrated." (PMID 24914105, 2014). "In a rat model of PCIBP, activation of microglia and astrocytes together with upregulation of IL-1β developed in the ipsilateral spinal cord of rats exhibiting pain behaviours at 20 days after unilateral ITI of rat prostate cancer cells." (PMID 23918298, 2013). "IL-1β expression has been reported to be closely related to LCN2 levels in prostate cancer cells." (PMID 40109857, 2025). "This review offers a general perspective on the implication of IL-1β in neoplastic diseases and mainly focuses on the role played by this cytokine in prostate cancer and particularly on the establishment and progression of skeletal metastases in the advanced form of the disease." (PMID 39858071, 2025). "This provided evidence for metastatic cooperation among different prostate cancer phenotypes via IL-1β signaling, which in addition to recruiting the bone stroma could also directly affect cancer cells through autocrine and paracrine stimulation." (PMID 39858071, 2025).
prostate carcinoma (continued). "Thus, the adoption of biomarker-informed treatments blocking IL-1β seems bound to significantly improve the clinical outcome of prostate cancer and other tumors, as shown by recent clinical trials with metastatic breast cancer patients." (PMID 39858071, 2025). "PC3-ML human prostate cancer cells express and secrete IL-1β." (PMID 39858071, 2025). "Moreover, IL-1β and IL-7R axis predominantly induces osteoblastic lesions and supports the skeletal colonization and metastatic progression of prostate cancer." (PMID 37127752, 2023). "These new findings indicate that the current prostate cancer standard of care will upregulate IL1β in patients presenting with secondary lesions with an exclusive or predominant ARPOS status similarly to patients with metastatic tumors harboring mostly or entirely ARNEG tumor cells." (PMID 36561929, 2022). "This discrepancy, which is to be expected considering the inevitable differences between established cell lines and human samples, suggests that methylation of multiple CpG sites on the IL1β promoter and gene body modulates the transcription of this cytokine in prostate cancer cells." (PMID 36561929, 2022). "Recent studies also reported that an increased NLRP12 expression is associated with the progression of prostate cancer in the absence of increased levels of mature IL-1β or IL-18 by cancer cells." (PMID 34203890, 2021). "In addition, it has been noted that IL-1β expression was elevated in prostate cancers that show a high tendency to metastasize." (PMID 34837692, 2021). "The IL-1β receptor antagonist anakinra is a potential useful drug for the treatment of prostate cancer bone metastasis, which can inhibit IL-1β -mediated recruitment and activation of MAFs, and its administration significantly impairs skeletal metastasis in an animal model." (PMID 34112258, 2021). "Similarly, prostate cancer cell-secreted IL-1β induces the transition of bone MSCs into CAFs in vitro and increases the expression of CAF markers in bone metastases in vivo." (PMID 34112258, 2021). "Persulfidation at Cys38 of the NF-κB p65 subunit facilitates nuclear translocation of p65 and then induces expressions of metastatic promoting genes, especially IL-1β, resulting in enhanced cell invasion and distant metastasis during prostate cancer progression." (PMID 34207284, 2021). "In vitro monocytic-derived IL-1β inhibits LNCaP prostate cancer proliferation or induces apoptosis." (PMID 32635472, 2020). "Through NF-κB, IL-1β induces the activation of epithelium-specific ETS (E26 transformation-specific) ESE1 (or E74-like factor (ELF3)), two ETS family members responsible for prostate cancer malignancy and associated with a poor prognosis for patients." (PMID 32635472, 2020). "Moreover, IL-1β silencing decreases metastatic potential of murine prostate cancer cells, while its overexpression increases it." (PMID 32635472, 2020). "In addition, the blackberry seed flour extract showed capacities for anti‐inflammation and antiproliferation by suppressing LPS induced IL‐1β mRNA expressions in the cultured J774A.1 mouse macrophages and the proliferation of LNCaP prostate cancer cells." (PMID 32148827, 2020). "Finally, IL-1β induces the expression of matrisylin in human LNCaP prostate cancer cells, a metalloprotease involved in cancer progression." (PMID 32635472, 2020). "In addition to the role of inflammasomes in IL-1β production, elimination of PKCε in prostate cancer cells also blocks production of IL-1β." (PMID 30158439, 2018). "The dominant expression of inflammasome complex proteins (ASC and pro-caspase-1) in aggressive prostate cancer cell lines implicate the role of NLRP12 inflammasome provoking inflammatory events via regulating IL-1β and IL-18 in the development and progression of prostate cancer." (PMID 28663562, 2017).
prostate carcinoma (continued). "It is likely that additional factors are required to activate and organize the formulation of NLRP12 inflammasome complex, similar to activation of AIM2 by the interferons (IFNs) in prostate cancer cell lines activating AIM2 inflammasome leading to interleukins IL-1β and IL-18 production." (PMID 28663562, 2017). "Since inflammasome assembly is considered a master regulator of inflammation, determining the molecular function of NLRP12 as an upstream regulator of NF-κB, IL-1β, and IL-18 signaling will add to our understanding the molecular basis of inflammation induced prostate cancer." (PMID 28663562, 2017). "Consequently inducing stem cell marker mRNA and protein accumulation, suggesting that IL-1β alters prostate cell fate and supports the notion that inflammation contributes to prostate cancer initiation and progression." (PMID 28927416, 2017). "IL-1β has been found to increase the formation as well as the resorptive capacity of osteoclasts in culture, and can induce IL-8 production in prostate cancer cells, which promotes prostate cancer cell proliferation and migration." (PMID 21206493, 2011). "In prostate cancer, a high lipid diet may accelerate tumor cell proliferation by increasing levels of insulin-like growth factor 1, IL-1α, IL-1β, IL -6, or TNF-α or through activation of signaling pathways such as MCP-1/CCR2 (monocyte chemoattractant protein-1/C-C Motif Chemokine Receptor 2)." (PMID 38028534, 2023). "Furthermore, a recent study demonstrated that an increased NLRP12 expression is associated with the progression of prostate cancer in the absence of increased levels of mature IL-1β or IL-18 by cancer cells." (PMID 36980199, 2023). "In summary, the present study suggests that cytokine gene polymorphisms, including IL-1β rs16944, IL-4 rs2070874, IL-4 rs2227284, IL-16 rs7175701, and IL-16 rs11556218 may not be risk factors for prostate cancer in a population in central China." (PMID 36034203, 2022). "Interestingly, a 10 s application of NIPP generated by a plasma jet in prostate carcinoma cells caused no change in the protein regulation of IL1B after 4 h." (PMID 36078148, 2022). "This suggested that IL‐1β may promote bone colonization by prostate cancer." (PMID 32761606, 2021). "Therefore, the homeostasis of normal prostate tissues and androgen-sensitive prostate cancers might be established by the driving force of androgen signaling and the inhibitory functions of inflammatory signaling, such as IL1β/IL1R1." (PMID 33322099, 2020). "An amplification loop may exist, as AR- cancers cells express high levels of IL-1β, while AR+ cells do not and androgen-deprivation drugs, that is, leuprolide and bicalutamide, inhibit prostate cancer cells’ mediated IL-1β secretion by peripheral blood mononuclear cells (PBMC) in vitro." (PMID 32635472, 2020). "Also, IL-1β supports the skeletal colonization and metastatic progression of prostate cancer cells." (PMID 27429614, 2016). "Prostate cancer is one of these diseases, and particularly in patients with its advanced form, the lack of AR expression—either constitutive or induced in AR-positive cells by paracrine IL-1β signaling—might be compounded by the functional inactivation of the AR by ADT/ARIs." (PMID 39858071, 2025). "Keywords like microbiota, radiotherapy, gene expression, prostatectomy, IL-6, IL-1β, TNF-α, and STAT3 hold central positions within the prostate cancer domain, reflecting their frequent study." (PMID 39355131, 2024). "The surprising discovery is in the prostate cancer group, the concentrations of the inflammatory cytokines IL-4, TNF-α, IL-1β, and IFN-α were significantly lower than those in the healthy control group (all p < 0.05)." (PMID 38833027, 2024). "Among others, keratin 81, CrkII, IL-1β, and cathepsin C were identified as proteins directly or indirectly targeted by CA2-2 in human prostate cancer cells." (PMID 38248645, 2023).
prostate carcinoma (continued). "To determine if tumors secrete mediators which can enhance the IL-1β and inflammasome activation in macrophages, we collected conditioned media (CM) from TRAMPC2 mouse prostate cancer cells overnight." (PMID 37449203, 2023). "Prostate cancer derived-EVs, by inducing NLRP3 activation and IL-1β maturation, modify the inflammatory response of ME residing cells in a tumor-promoting fashion." (PMID 35530309, 2022). "For instance, DU-145 prostate cancer cells are ARNEG and yet fail to express the IL1β protein or its transcript." (PMID 36561929, 2022). "We showed that advanced-stage prostate cancer PC3 cells display constitutively activated NLPR3-inflammasome that mediates the conversion of the IL-1β precursor to the secreted and active form of IL-1β." (PMID 34070682, 2021). "In this paper we showed that, compared to LNCaP cells, advanced-stage prostate cancer PC3 cells display constitutively high levels of active caspase-1 and actively secrete IL-1β." (PMID 34070682, 2021). "Our data on only little induction of IL1β and IL6 in myeloid cells by prostate cancer cell-derived supernatants are in line with previous findings." (PMID 32316245, 2020). "With regard to NF-κB pathway function in prostate cancer cells, the influence of the canonical NF-κB pathway activation agonists such as TNF and IL-1β is relatively well characterized." (PMID 27975057, 2016). "The gene list contains inflammatory genes such as IL-6, IL-8, IL1β and COX-2, which have extensive connections to prostate cancer." (PMID 23342084, 2013). "A panel of pharmacological inhibitors of MAP kinases produced variable effects on IL-1β- and TNF-α-induced shedding of EPCR in DU-145 and PC-3 prostate cancer cells." (PMID 21320357, 2011). "In a prostate cancer model, mice lacking IL-1β exhibited impaired tumor progression and angiogenesis." (PMID 40718836, 2025). "Furthermore, analysis of the TCGA PRAD cohort revealed a significant correlation between expression of FUT8 and genes for IGFBP5, IL1B and PTGES3 in clinical prostate cancer tissue." (PMID 40387385, 2025). "BPH tissues and prostate cancer cells express toll-like receptor 4 (TLR4) and are characterized by increased immune-mediated inflammatory processes and secretion of cytokines, such as IL-1β, IL-6, IL-8, TNF-α, and COX-2." (PMID 36771389, 2023). "In agreement with previous studies in breast and prostate cancers, these results indicate that IL-1β does not promote cell-autonomous growth advantages to lung adenocarcinoma cells in vitro." (PMID 37985999, 2023). "Researchers have found that alternol induces ICD in prostate cancer cell lines by increasing DAMPs levels (HMGB1, ATP release, and CRT translocation; pro-inflammatory cytokines such as IL-1 A, IL-1B, IL-8, and IL-6) and stimulating the immune response against tumors in prostate cancer cells." (PMID 37705051, 2023). "Findings were also null for CRP, IL-1β, and TNF-α in these two prostate cancer cohorts." (PMID 37213604, 2023). "Targeting IL‐1β and blocking immune checkpoints in combination with ADT could be a promising therapeutic approach for advanced prostate cancer." (PMID 37092583, 2023). "Prostate cancer cells lacking AR are inherently refractory to AR-targeted therapies and can express IL1β at any stage of clinical progression." (PMID 36561929, 2022). "Thus, to model the AR/IL1β inverse correlation from patients with skeletal metastatic disease, we grafted GFP-expressing LNCaP prostate cancer cells directly into the tibiae of hormone-intact mice." (PMID 36561929, 2022). "In prostate cancer, overexpression of CTH increased H2S production leads to the activation of nuclear factor-κB (NF-κB)-mediated interleukin 1β (IL-1β) signaling, resulting in the enhanced cell invasion, angiogenesis, lymphangiogenesis, tumor growth, and metastasis in prostate cancer." (PMID 34207284, 2021).
prostate carcinoma (continued). "We found that the advanced stage prostate cancer PC3 cells, exhibit comparable NLRP3 protein expression level but higher pro-IL-1β and active P-20 fragment of caspase-1, paralleled by doubled IL-1β secretion level after 48 h of culture compared to the androgen-sensitive LNCaP cells." (PMID 34070682, 2021). "Prostate cancer cells express chemokine and chemokine receptors, as well as endogenously produced chemokines and cytokines such as MCP-1, TNF-α, IL-1β, IL-6, and IL-8, some of which are secreted at a higher level in PC-3 cells (mCRPC cell line) than in LNCaP cells (mCSPC cell line)." (PMID 33050597, 2020). "IL-6, IL-8, and TNF-α, but not IL-1β, are upregulated in prostate carcinoma (CaP) patients with CC compared with those without CC." (PMID 30513776, 2018). "In accordance with prostate cancer patients undergoing radiotherapy, fatigue severity reached a maximum after 4 weeks of treatment; IL-1β concentrations in serum did not change and did not correlate with fatigue severity." (PMID 28109186, 2017). "Further investigations on prostate cancer using a mouse model, found that overexpression of IL-1β in non-metastatic prostate cancer cells promoted bone metastasis, whereas its knockdown impaired bone invasion by metastatic cells." (PMID 28927416, 2017). "We found a reduction in NF-κB (p65), IL-1β, and Vimentin and upregulation of E-cadherin protein levels in MTA1 knockdown (shMTA1) prostate cancer cells, suggesting direct involvement of MTA1 in inflammation and EMT in prostate cancer." (PMID 26943043, 2016). "In this study, overexpression of IL-1B in non-metastatic prostate cancer cells promoted bone metastasis, whereas knockdown of IL-1B impaired bone progression by metastatic cells." (PMID 27765923, 2016). "Although induction of these chemokines by IL1β has not beendemonstrated to date, several pieces of evidence support the relevance of thismechanism in prostate cancer progression." (PMID 21479216, 2011). "The Top 5 GO molecular functions for the most influential biomarkers in the ABCD‐prostate cancer oncogenic network (IL‐1β, MCP‐1, and CXCL1) are consistently related to glycosaminoglycan/integrin binding and immune receptor activity (predominantly as IL‐1β function)." (PMID 41450167, 2026). "Since IL-18 and IL-1β are produced in large quantities during NLRP3 inflammasome activation, current findings indicate that the NLRP3 inflammasome and its downstream pathways may promote prostate cancer progression." (PMID 40718836, 2025). "A particularly striking scenario is the bone metastatic niche in which prostate cancer cells, either lacking the AR or with this receptor inactivated by therapy, produce and secrete IL-1β, which is normally repressed by the binding of the AR to at least one ARE half-site near the IL-1β promoter." (PMID 39858071, 2025). "In addition to the growth and progression of prostate cancer itself, research has been proposed that exosome PSGR1 might regulate MAPK and NF-κB signaling pathways involved in prostate cancer bone metastasis by targeting ICAM1, RELB, and IL1B." (PMID 41347146, 2025). "Notably, an inactive AR signaling does not unleash IL-1β expression in all prostate cancer phenotypes." (PMID 39858071, 2025). "Notably, the conditioning of the bone metastatic niche by IL-1β secreted by PC3-ML cells supported the survival and growth of prostate cancer cells such as LNCaP cells (growing within the same skeletal tumors) that otherwise would have failed to colonize the bone." (PMID 39858071, 2025). "Finally, it has been demonstrated that IL-1β is necessary but not sufficient for metastasis of prostate cancer cells." (PMID 36836748, 2023). "Thus, in patients with prostate cancer harboring ARNEG tumor cells or treated with androgen-deprivation therapy/ARIs, and with the IL1β gene unmethylated, IL1β could condition the metastatic microenvironment to sustain disease progression." (PMID 36561929, 2022).